FUS (FUS RNA binding protein)
Diseases named in the same sentence as FUS in open-access papers (continued):
Sharing a sentence is not in itself a finding about the gene and the disease.
amyotrophic lateral sclerosis (continued). "Genetic mutations in fused in sarcoma (FUS) cause amyotrophic lateral sclerosis (ALS)." (PMID 36163369, 2022). "FUS, a DNA/RNA binding protein, has been intensively studied for its role in neurodegeneration, especially amyotrophic lateral sclerosis." (PMID 35396503, 2022). "For example, PURα colocalized with mutant FUS in stress granules to modulate amyotrophic lateral sclerosis (ALS) pathology." (PMID 35945453, 2022). "For example, in ALS (amyotrophic lateral sclerosis) mutations, the FUS protein phase separates into abnormal neuronal granules, and ectopic aggregates of FMRpolyG protein in ovarian stromal cells are associated with Fragile-X-associated primary ovarian insufficiency." (PMID 35801939, 2022). "For instance, mutant R521C stabilizes FUS in amyotrophic lateral sclerosis (ALS) patients, facilitating its interaction with RBM45, and decreases the recruitment of HDAC1 to contribute to the pathogenesis of ALS16." (PMID 35654793, 2022). "Such prion-like proteins have been linked to pathomechanisms of amyotrophic lateral sclerosis (ALS) in humans, in particular TDP43, FUS, TAF15, EWSR1 and hnRNPA2." (PMID 36415860, 2022). "Fused in sarcoma (FUS) is a pathogenic RNA-binding protein in amyotrophic lateral sclerosis (ALS)." (PMID 36261283, 2022). "Accumulation of cytoplasmic inclusions containing fused in sarcoma (FUS), an RNA/DNA-binding protein, is a common hallmark of frontotemporal lobar degeneration and amyotrophic lateral sclerosis neuropathology." (PMID 35709984, 2022). "For instance, the liquid-to-solid phase transition of FUS protein is related to amyotrophic lateral sclerosis (ALS)." (PMID 34404453, 2021). "Gene mutations causing cytoplasmic mislocalization of the RNA-binding protein FUS lead to severe forms of amyotrophic lateral sclerosis (ALS)." (PMID 34021132, 2021). "Mutations disrupting the nuclear localization of the RNA-binding protein FUS characterize a subset of amyotrophic lateral sclerosis patients (ALS-FUS)." (PMID 34021139, 2021). "In 2009, mutations in FUS were shown to be causative for Amyotrophic Lateral Sclerosis (ALS)." (PMID 34233002, 2021). "Many proteins (e.g., FUS, TDP-43, TIA1, tau, α-synuclein) associated with Parkinson’s disease or amyotrophic lateral sclerosis (ALS) also undergo LLPS and are constituents of different types of MLOs." (PMID 34884563, 2021). "The amyotrophic lateral sclerosis (ALS) neurodegenerative disorder has been associated with multiple genetic lesions, including mutations in the gene for fused in sarcoma (FUS), a nuclear-localized RNA/DNA-binding protein." (PMID 33148607, 2020). "This is particularly the case for amyotrophic lateral sclerosis (ALS), a multigenic disease resulting from mutations in various genes including superoxide dismutase (SOD1), TDP43 or FUS protein." (PMID 32961072, 2020). "Mutations in the RNA binding protein FUS cause amyotrophic lateral sclerosis (ALS)." (PMID 33311468, 2020). "A phenotype common in neurodegenerative diseases is aggregation of nuclear or cytoplasmic proteins with IDRs—this includes TAU in Alzheimer's disease and TDP-43 and FUS in amyotrophic lateral sclerosis (ALS) and frontotemporal dementia (FTD)." (PMID 32364240, 2020). "Notable examples include the liquid-like condensates and further phase transition into hydrogel by amyotrophic lateral sclerosis (ALS) mutants of FUS or hnRNPA19,19,20." (PMID 32005838, 2020). "Genetic mutations in FUS, a DNA/RNA‐binding protein, are associated with inherited forms of frontotemporal lobar degeneration (FTLD) and amyotrophic lateral sclerosis (ALS)." (PMID 32667139, 2020). "The motor protein kinesin-5 is associated with RBPs such as Fragile X mental retardation protein (FMRP, a causative gene product of Fragile X syndrome) and fused in sarcoma (FUS), which are related to amyotrophic lateral sclerosis and frontotemporal dementia." (PMID 32344905, 2020).
amyotrophic lateral sclerosis (continued). "Consistent observations in the same line of FUS, also the ALS‐associated TDP‐43 protein was reported to be present in exosomes from primary neurons of human amyotrophic lateral sclerosis brains and plasma of ALS patients." (PMID 33391635, 2020). "For example, phosphorylation of amyotrophic lateral sclerosis (ALS)-related RBP fused in sarcoma (FUS) reduces the protein’s propensity to aggregate." (PMID 33330512, 2020). "Four genes linked to familial cases of amyotrophic lateral sclerosis were investigated for antisense transcription: SOD1, FUS, TARDBP, and UBQLN2." (PMID 30610612, 2019). "Mutations in the FUS gene cause amyotrophic lateral sclerosis (ALS-FUS)." (PMID 30642400, 2019). "Mutations in the FUS gene cause familial amyotrophic lateral sclerosis (ALS-FUS)." (PMID 31875556, 2019). "TDP-43 and FUS are nuclear proteins with multiple functions in mRNA processing, which have been involved in amyotrophic lateral sclerosis (ALS) and frontotemporal lobar degeneration (FTLD)." (PMID 31023421, 2019). "It has been shown that mutation in FUS and TARDBP are associated with amyotrophic lateral sclerosis(ALS), a motor neuron disease by leading to neuronal cell death." (PMID 31017923, 2019). "Both familial and sporadic Amyotrophic Lateral Sclerosis (ALS) is associated with cytosolic aggregation of proteins, most frequently TDP-43, with FUS and SOD1 seen in some familial cases." (PMID 31783880, 2019). "These FUS protein aggregates are known as pathological hallmarks in a subset of amyotrophic lateral sclerosis (ALS) and frontotemporal lobar degeneration (FTLD) cases." (PMID 30002616, 2018). "Mutations in fused in sarcoma (FUS) cause amyotrophic lateral sclerosis (ALS)." (PMID 29430619, 2018). "FUS, a RNA binding protein associated with neurodegenerative diseases, including amyotrophic lateral sclerosis (ALS) and frontotemporal lobar degeneration (FTLD), is involved in multiple steps of RNA processing, such as transcription, splicing, transport and translation." (PMID 29412139, 2018). "Since 2009, FUS has received more attention for its connection to neurodegenerative disease after missense mutations were discovered to cause a small percentage of cases of amyotrophic lateral sclerosis (ALS-FUS)." (PMID 29547565, 2018). "Subcellular mislocalization and aggregation of the human FUS protein occurs in neurons of patients with subtypes of amyotrophic lateral sclerosis and frontotemporal dementia." (PMID 29547565, 2018). "Cabeza (caz) is the single Drosophila melanogaster orthologue of the human FET proteins FUS, TAF15, and EWSR1, which have been implicated in amyotrophic lateral sclerosis (ALS) and frontotemporal dementia." (PMID 30209068, 2018). "Mutations associated with amyotrophic lateral sclerosis (ALS) appear in the proteins SOD1, FUS, TDP-43, and OPTN which become misfolded and aggregate." (PMID 30083092, 2018). "Some paraspeckle proteins, such as TDP-13, FUS, EWS, TAF15, HNRNPA1, SS18L1, and SFPQ have been associated with neuro-degenerative diseases, such as amyotrophic lateral sclerosis (ALS) and frontotemporal dementia (FTD)." (PMID 30087896, 2018). "Recently, Tar DNA-binding protein-43 (TDP-43) and Fused in Sarcoma (FUS), two proteins intimately linked to fronto-temporal dementia and related amyotrophic lateral sclerosis (FTD/ALS) have also been shown to disrupt ER–mitochondria associations." (PMID 28337542, 2017). "Abnormal functions of RNA-binding proteins TAF15, FUS and TDP43 are associated with amyotrophic lateral sclerosis." (PMID 27378374, 2016). "The FET protein family includes FUS, EWS and TAF15 proteins, all of which have been linked to amyotrophic lateral sclerosis, a fatal neurodegenerative disease affecting motor neurons." (PMID 27117089, 2016). "Aβ and tau form aggregates in AD and related tauopathies, as does α-synuclein in Parkinson disease and TDP-43 and FUS in amyotrophic lateral sclerosis." (PMID 27030011, 2016).
amyotrophic lateral sclerosis (continued). "A conspicuous number of RNA binding proteins (RBPs) have been shown to be associated with amyotrophic lateral sclerosis (ALS) or other neuromuscular diseases: for example, mutations in RBPs such as hnRNPA1 and A2B1, TDP-43, and FUS are associated with ALS." (PMID 28082869, 2016). "Familial mutations in FUS linked to amyotrophic lateral sclerosis (ALS) decrease an interaction with the histone deacetylase HDAC1 and produce a FUS protein defective in DNA repair and DDR." (PMID 26529031, 2015). "Here, we have taken advantage of in vitro iPSCs derived from patients affected by amyotrophic lateral sclerosis (ALS) and carrying mutations in the RNA-binding protein FUS to study the cellular behavior of the mutant proteins in the appropriate genetic background." (PMID 26035390, 2015). "Genetic mutations in RNA-binding proteins FUS and TDP-43 have been linked with causing neurodegenerative diseases: amyotrophic lateral sclerosis and frontotemporal dementia." (PMID 26047658, 2015). "Genes encoding RNA-binding proteins, including FUS and TDP43, play a central role in different neurodegenerative diseases such as amyotrophic lateral sclerosis and frontotemporal lobar degeneration." (PMID 25375143, 2014). "Five to 10% of cases of amyotrophic lateral sclerosis are familial, with the most common genetic causes being mutations in the C9ORF72, SOD1, TARDBP and FUS genes." (PMID 23228179, 2013). "In addition to its role in oncogenesis, mutations in FUS have been recently reported to cause a familial form of amyotrophic lateral sclerosis (ALS)." (PMID 23056579, 2012). "Familial amyotrophic lateral sclerosis (ALS) related mutations are clustered in FUS-NLS." (PMID 23056579, 2012). "Mutations in the FUS, EWS, and the TAF15 genes are reported in familiar and sporadic amyotrophic lateral sclerosis (ALS)." (PMID 23049996, 2012). "The DNA/RNA-binding proteins TDP-43 and FUS are found in protein aggregates in a growing number of neurodegenerative diseases, including amyotrophic lateral sclerosis (ALS) and related dementia, but little is known about the neurotoxic mechanisms." (PMID 22848727, 2012). "Two proteins mutated in familial cases of amyotrophic lateral sclerosis (ALS) or FTLD, the RNA-binding proteins TAR DNA-binding protein-43 (TDP-43) and fused in sarcoma (FUS), have been identified in Microprocessor complexes." (PMID 23115562, 2012). "Furthermore, connections with FUS, TARDBP, and NEFL, all linked to amyotrophic lateral sclerosis (ALS), highlight SOD1’s involvement in neurodegenerative disease pathways." (PMID 40710578, 2025). "Notable examples are HD, caused by an expansion in the huntingtin gene (HTT), and certain familial forms of amyotrophic lateral sclerosis (ALS) that are considered monogenic, associated with mutations in SOD1 (superoxide dismutase), TARDBP (Transactive response DNA-binding protein), or FUS." (PMID 39857412, 2025). "In addition, FUS regulates circRNA formation in neurons, and its mutation may contribute to the pathogenesis of amyotrophic lateral sclerosis (ALS)." (PMID 39859439, 2025). "An international study is currently underway to shed light on the natural history of ALS patients carrying FUS mutations (NH00004, A Retrospective Chart Review Study of the Natural History and Disease Progression in Amyotrophic Lateral Sclerosis Patients with Fused in Sarcoma Mutations, FUS‐ALS)." (PMID 39976178, 2025). "Spinal Muscular Atrophy (SMA) and Amyotrophic Lateral Sclerosis (ALS) share phenotypic and molecular commonalities, including the fact that they can be caused by mutations in ubiquitous proteins involved in RNA metabolism, namely SMN, TDP-43 and FUS." (PMID 37759179, 2023). "Furthermore, point mutations in FUS and TAF15 are associated with neurodegenerative conditions like amyotrophic lateral sclerosis and frontotemporal lobar dementia." (PMID 37961424, 2023).
amyotrophic lateral sclerosis (continued). "Regarding amyotrophic lateral sclerosis (ALS), researchers have discovered several mutations of the FUS gene that may contribute to its progression." (PMID 37445986, 2023). "FUS variants can cause rare juvenile, aggressive genetic forms of amyotrophic lateral sclerosis (ALS), with FUS protein localisation shifting from the nucleus to the cytoplasm, accompanied by FUS cytoplasmic aggregation in motor neurons and glia of the motor cortex and spinal cord." (PMID 37772684, 2023). "To illustrate this point, we have analyzed mutations in droplet-forming proteins, FUS (G156E, G187S), TDP-43 (A321V, A315T), TAU (P301L), TIA-1 (E384K), hnRNPA2 (D214V, D290V), UBQLN2 (P506T), which are associated with amyotrophic lateral sclerosis (ALS)." (PMID 36416856, 2022). "Loss of function or missense variants in the gene encoding FUS, one of the main components of the aggregates of FTLD-FET cases, typically cause amyotrophic lateral sclerosis (ALS), a motor neuron disease that shares overlapping genetic and pathological features with FTD." (PMID 35151370, 2022). "Prominently, toxic protein aggregation such as those formed by β-amyloid peptide (Aβ) and tau proteins in Alzheimer’s disease, TDP-43/FUS in amyotrophic lateral sclerosis (ALS), and huntingtin protein in Huntington’s disease have been studied as archetypical phase separation processes." (PMID 33168632, 2021). "Proteins related to neurodegenerative disease were also found to be significantly changed in abundance, including proteins involved in Parkinson’s disease (PARK7) and amyotrophic lateral sclerosis (ubiquilin-4, superoxide dismutase, and RNA-binding protein FUS)." (PMID 34073856, 2021). "Mutations affecting several RBPs, including FUS, TDP-43, hnRNPA1, hnRNPA2B1, matrin-3, and TIA1, are linked to amyotrophic lateral sclerosis (ALS), frontotemporal dementia (FTD), multisystem proteinopathy (MSP), and hereditary inclusion body myopathy (hIBM) phenotypes." (PMID 34291734, 2021). "First links between ArgMet and neurodegenerative diseases have been suggested, as hypomethylated RNA-binding proteins FUS and poly-GR dipeptide repeats were found to be enriched in patients with frontotemporal dementia and amyotrophic lateral sclerosis, respectively." (PMID 35475236, 2021). "In ALS (Amyotrophic lateral sclerosis), an RNA binding protein (FUS) is a new regulator of controlling circRNA expression in mouse motor neurons and controls the splicing of novel and unknown transcripts." (PMID 32467674, 2020). "Genetic analyses of patients with amyotrophic lateral sclerosis (ALS) have revealed a strong association between mutations in genes encoding many RNA-binding proteins (RBPs), including TARDBP, FUS, hnRNPA1, hnRNPA2B1, MATR3, ATXN2, TAF15, TIA-1, and EWSR1, and disease onset/progression." (PMID 32547363, 2020). "A number of neuromuscular and muscular diseases, including amyotrophic lateral sclerosis (ALS), spinal muscular atrophy (SMA) and several myopathies, are associated to mutations in related RNA-binding proteins (RBPs), including TDP-43, FUS, MATR3 or hnRNPA1/B2." (PMID 32292882, 2020). "Furthermore, recent neurodegenerative studies have identified the presence of amyloidogenic TDP-43, FUS, and hnRNP A/B (in Amyotrophic Lateral Sclerosis) and amyloidogenic tau (in Frontotemporal Dementia) in LLPS organelles in brain cells." (PMID 33330512, 2020). "For example, mutations in the genes encoding the RBPs Fused in sarcoma (FUS) and TAR DNA-binding protein 43 (TDP-43) have been linked to the pathogenesis of amyotrophic lateral sclerosis, and the proteins were depleted from the nucleus and aggregated in the cytoplasm in affected neurons." (PMID 33193718, 2020). "Since this discovery, several other human RNA-binding proteins with prion-like domains associated with disease were identified including, for instance, FUS, TDP-43 and TAF15 that are linked to amyotrophic lateral sclerosis (ALS) and frontotemporal dementia (FTD)." (PMID 33068411, 2020).
amyotrophic lateral sclerosis (continued). "Amyotrophic lateral sclerosis (ALS) is a lethal disease characterized by motor neuron degeneration and associated with aggregation of nuclear RNA-binding proteins (RBPs), including FUS." (PMID 30937520, 2019). "FUS has long been considered as a key player in neuronal cell-related diseases, and a recent study revealed that FUS protein mislocalization in amyotrophic lateral sclerosis (ALS) could be an underlying mechanism for this disorder." (PMID 31766457, 2019). "In this context, it would be intriguing to note that a number of paraspeckle-enriched RBPs with IDRs, including SFPQ, FUS, EWSR1, TAF15, TDP-43, SS18L1 and HNRNPA1, are mutated in familial cases of amyotrophic lateral sclerosis (ALS) and other neurodegenerative diseases." (PMID 30355755, 2018). "This study may provide a novel insight into FMRP involvement in the intracellular localization of FUS and pathology of FUS-related amyotrophic lateral sclerosis." (PMID 28424484, 2017). "For example, the human proteins TDP-43 and FUS are critical for amyotrophic lateral sclerosis (ALS), but there may be other important genes involved in related disorders." (PMID 26462863, 2016). "Accordingly, recruitment of FUS, hnRNPA1 and hnRNPA2/B1 to cytoplasmic stress granules was observed in vitro and in a subpopulation of patients with the progressive neurodegenerative disease amyotrophic lateral sclerosis (ALS)." (PMID 25699204, 2015). "Dysfunction of two structurally and functionally related proteins, FUS and TAR DNA-binding protein of 43 kDa (TDP-43), implicated in crucial steps of cellular RNA metabolism can cause amyotrophic lateral sclerosis (ALS) and certain other neurodegenerative diseases." (PMID 23867462, 2013). "The prion-like protein FUS, known for forming insoluble aggregates in neurodegenerative diseases such as frontotemporal dementia and amyotrophic lateral sclerosis (ALS), also forms viscous condensates in aged HSCs under physiological conditions." (PMID 40738832, 2026). "For example, RNA-binding proteins such as TDP-43 and FUS normally form dynamic liquid droplets, but in neurodegenerative conditions like amyotrophic lateral sclerosis (ALS) and frontotemporal dementia (FTD), they accumulate as insoluble fibrillar inclusions." (PMID 41383708, 2025). "Amyotrophic lateral sclerosis (ALS) and frontotemporal dementia (FTD) are incurable neurodegenerative disorders sharing pathological and genetic features, including mutations in the FUS gene." (PMID 39852477, 2025). "Mutations in Fused in Sarcoma (FUS) are associated with neurodegenerative disorders, including amyotrophic lateral sclerosis (ALS) and frontotemporal dementia (FTD)." (PMID 41245603, 2025). "Approximately 40–55% of amyotrophic lateral sclerosis (ALS) cases are attributed to mutations in over 50 identified ALS-associated genes; among these, pathogenic mutations in SOD1, C9ORF72, FUS, and TARDBP are the most prevalent." (PMID 38927671, 2024). "FUS and TDP-43, two RNA-binding proteins from the heterogeneous nuclear ribonucleoprotein family, have gained significant attention in the field of neurodegenerative diseases due to their association with amyotrophic lateral sclerosis (ALS) and frontotemporal degeneration (FTD)." (PMID 38029395, 2024). "Here, we report that HTRA1 inhibits aggregation of α-syn as well as FUS and TDP-43, which are implicated in amyotrophic lateral sclerosis (ALS) and frontotemporal dementia." (PMID 38499535, 2024). "Here the authors report that HTRA1 inhibits aggregation of α-syn as well as FUS and TDP-43, which are implicated in amyotrophic lateral sclerosis (ALS) and frontotemporal dementia." (PMID 38499535, 2024). "The phenotypic defect would be exacerbated by the disruption of two amyotrophic lateral sclerosis (ALS) genes encoding the proteins TDP-43 and FUS." (PMID 37894677, 2023).